MIF (macrophage migration inhibitory factor)
Diseases named in the same sentence as MIF in open-access papers (continued):
Sharing a sentence is not in itself a finding about the gene and the disease.
chronic kidney disease (14 papers, 2010 to 2025). Impairment of the renal function secondary to chronic kidney damage persisting for three or more months. "Our data indicate that some polymorphisms, IL6rs1800795 and MIF rs755622, involved in the regulation of both renal function and inflammatory response can influence the evolution of chronic kidney disease." (PMID 35205271, 2022). "Our findings are similar to other meta-analyses of MIF, where the C allele was found to be more common within CAD patients and those with chronic kidney diseases." (PMID 38476376, 2024). "In this light, further studies will certainly be needed to investigate the role and interaction of these SNPs, in particular MIF rs755622, in the progression of end-stage renal disease." (PMID 35205271, 2022). "An important risk factor for postoperative AKI is pre-existing chronic kidney disease (CKD), genetic studies support an association between the presence of at least one MIF G>C allele (rs755622) with chronic kidney and cardiovascular disease." (PMID 32932965, 2020). "Systemic MIF concentrations are elevated in patients with chronic kidney disease and in septic patients with AKI." (PMID 28813470, 2017). "A significant difference in the genotype frequency of high production MIF -173 G/C genotype has been found in end-stage renal disease, compared to controls." (PMID 26858715, 2016). "MIF has been shown to play a critical role in chronic kidney disease (CKD)." (PMID 35563296, 2022). "Since recent data suggest that MIF can be effectively removed from the circulating blood pool in patients with chronic kidney disease, we here aimed to investigate whether RRT in septic shock can lower plasma levels of this pro-inflammatory cytokine in septic shock patients." (PMID 27313864, 2016). "Also, MIF is abundantly secreted in end-stage chronic kidney disease (CKD) and is filtered during hemodialysis." (PMID 40426915, 2025).
leukemia (14 papers, 2017 to 2025). A malignant (clonal) hematologic disorder, involving hematopoietic stem cells and characterized by the presence of primitive or atypical myeloid or lymphoid cells in the bone marrow and the blood. "In a mouse retroviral model of AML, MIF produced by a FLT3-mutated subclone was observed to favor the expansion of leukemia-initiating cells." (PMID 35115654, 2022). "High MIF expression (Macrophage Inhibitory Factor) has been recently linked to worse outcomes and high relapse in leukemia patients (see discussion)." (PMID 34489550, 2021). "High MIF expression (Macrophage Inhibitory Factor) has been recently linked to worse outcome and high relapse in leukemia patients (see discussion)." (PMID 34354240, 2021). "Proteomic analyses confirmed a higher expression of MIF in a majority of KMT2A-MLLT3 leukemias with an activating mutation." (PMID 29720585, 2018). "Overexpression of HIF-1α confers doxorubicin resistance in AML cells and synergizes with leukemia-derived macrophage migration inhibitory factor (MIF) to enhance cellular proliferation and survival." (PMID 40791591, 2025). "In xenograft models, treatment with MIF inhibitor 4-IPP reduces leukemia burden, and with GM-CSF has a profound effect on the TME in vivo, notably on malignant tissue vasculature." (PMID 38548753, 2024). "MIF has been recently identified as a critical target correlated with a worse outcome in leukemia patients, as it was defined as an independent prognostic factor important for OS and DSF." (PMID 34354240, 2021). "MIF has been recently identified as a critical target gene that correlated with a worse outcome in leukemia patients, as it was defined as an independent prognostic factor important for OS and DSF." (PMID 34489550, 2021). "Although UBIQUITIN did not stimulate growth or survival of MLL-AF9 leukemia cells in vitro, there was a slight but dose-dependent increase in leukemia cell numbers when supplementing the culture medium with MIF." (PMID 32460032, 2020). "MIF, a pro-inflammatory cytokine, was highly expressed in KMT2A-MLLT3 leukemia with activating mutations both in mice and in primary infant ALL patients." (PMID 29720585, 2018). "In this work, we show that inhibiting MIF induces the death of leukemia cell lines and primary blasts and reprograms M2-like MΦ orientation when combined with GM-CSF, leading to blast cell death and reversal of resistance to therapies targeting FLT3-ITD or BCL-2 in vitro." (PMID 38548753, 2024). "We show that MIF inhibition reduces leukemia cell proliferation by 24–48 h." (PMID 38548753, 2024). "Indeed, using intravital imaging, we show that MIF inhibition combined with GM-CSF administration in preclinical models reduces leukemia burden and results in a striking inhibition of angiogenesis in the TME in vivo, accompanied by a shift in MΦ phenotype." (PMID 38548753, 2024). "Additionally, hypoxia is reported to promote secretion of MIF in NK cells and induce apoptosis of leukemia target cells." (PMID 35842634, 2022). "To address whether MIF promotes leukemia cells in a CXCR4-dependent manner, we evaluated whether leukemia cells with Cxcr4 disruption responded to MIF." (PMID 32460032, 2020). "Neutrophils infiltration could also be induced by MIF produced by leukemia cells." (PMID 35842634, 2022). "Herein, we show that one such factor, MIF, promotes survival of mouse KMT2A-MLLT3 leukemia initiating cells." (PMID 29720585, 2018). "Using intravital imaging in mice, we also show that treatment with MIF inhibitor 4-IPP and GM-CSF profoundly affects the tumor microenvironment in vivo: it strikingly inhibits tumor vasculature, reduces protumoral MΦ, and slows down leukemia progression." (PMID 38548753, 2024).
leukemia (continued). "There were many leukemia-related genes in the up-regulated genes of K1 group, such as UBB (P=1.56e-50), MIF (P=2.76e-50), DRAP1 (P=1.72e-49), RPS25 (P=1.9e-49), EIF3K (P=4.77e-49), SSNA1 (P=1.27e-48), GPX4 (P=3.01e-48), PHB2 (P=7.13e-48), NME2 (P=2.44e-47) or CFL1 (P=4.07e-47)." (PMID 36408189, 2022). "Compared with leukemia cells expressing normal Cxcr4 levels, Cxcr4 deletion did not affect MIF-induced growth or survival of leukemia cells." (PMID 32460032, 2020). "Because we found that CXCL12 is dispensable for AML development, we next assessed whether UBIQUITIN or MIF promotes growth and survival of MLL-AF9 leukemia cells by binding to CXCR4." (PMID 32460032, 2020). "Given that MIF influenced the survival of KMT2A-MLLT3 leukemia cells ex vivo, we next assessed whether MIF stimulation maintained leukemia-initiating cells (LICs) ex vivo using a transplantation assay." (PMID 29720585, 2018). "We found that MIF positively influenced survival of KMT2A-MLLT3 leukemia cells when cultured without IL3." (PMID 29720585, 2018). "MIF (but not DDT) is highly overexpressed in cells derived from leukemia’s (MOLT-4, K-562, and HL-60) and Burkett’s lymphomas (Daudi and Raji)." (PMID 29247872, 2017). "This approach might also preserve the graft versus leukemia response and aligns with the role of MIF in inflammation progression and exacerbation rather than initiation." (PMID 40421032, 2025). "Furthermore, M-CSF, macrophage migration inhibitory factor (MIF), IL-8, and CCL2 may promote a protumoral MΦ polarization contributing to forming a protective niche for leukemia stem cells." (PMID 34771453, 2021). "Taken together, our data suggest that CXCR4 signaling is essential for growth and survival of MLL-AF9 leukemia cells independent of CXCL12, MIF, and UBIQUITIN stimulation." (PMID 32460032, 2020).
ulcerative colitis (14 papers, 2009 to 2024). An inflammatory bowel disease involving the mucosal surface of the large intestine and rectum. "MIF is also implicated in the pathogenesis of ulcerative colitis through activation of pro-inflammatory cytokines and subsequent anti-steroid effects." (PMID 34576214, 2021). "In ulcerative colitis patients, refraction to GC treatments correlated with higher levels of MIF in lamina propria macrophages, which resulted in p38 activation, and reduced inhibition of IL-8." (PMID 34576214, 2021). "MIF is constitutively expressed in epithelial cells from the intestinal tract, and its expression is enhanced during ulcerative colitis, promoting inflammation and the development of severe pathology." (PMID 31360118, 2019). "In patients with ulcerative colitis, MIF may induce mucosal damage by promoting macrophage infiltration in local intestinal mucosa and inducing macrophage to produce IL-8." (PMID 35815289, 2022). "The importance of MIF for inflammatory conditions is reflected by the high levels of this cytokine found in patients with diabetes mellitus, rheumatoid arthritis, multiple sclerosis, atherosclerosis, asthma, inflammatory liver disease, ulcerative colitis, and cancer." (PMID 31360118, 2019).
vitiligo (14 papers, 2014 to 2025). Generalized well circumscribed patches of leukoderma that are generally distributed over symmetric body locations and is due to autoimmune destruction of melanocytes. "Linear regression analysis was done for the prediction of higher disease extent as a sign of disease severity within vitiligo patients, using age, gender, family history, onset, course, and MIF genotypes as risk factors." (PMID 40445486, 2025). "We tried to investigate the association between MIF (rs755622) gene polymorphism and vitiligo susceptibility and its relationship to severity and clinical types of the disease." (PMID 40445486, 2025). "Within healthy control subjects, vitiligo development was predicted via logistic regression analysis, using age, gender, family history, and MIF genotypes as risk factors." (PMID 40445486, 2025). "Through the logistic regression analysis conducted for the prediction of vitiligo development within healthy control subjects, using age, gender, and MIF (rs755622) genotypes as risk factors." (PMID 40445486, 2025). "The aim of this study was to investigate the association between MIF (rs755622) gene polymorphism and vitiligo susceptibility and its relationship to severity and clinical types of the disease among the studied group of patients." (PMID 40445486, 2025). "MIF (GC + CC) gene polymorphism genotypes were considered independent significant predictors for vitiligo development within healthy control subjects (p < 0.001)." (PMID 40445486, 2025). "Macrophages and the macrophage migration inhibitory Factor (MIF) they secrete are associated with the severity of vitiligo." (PMID 40703229, 2025). "Previous studies have found that macrophage inhibitory factor (MIF) gene polymorphisms and serum MIF and MIF mRNA levels are significantly higher in vitiligo patients than in healthy people, which was consistent with our results." (PMID 33679890, 2021). "That is why in this study, the influence of −794 CATT5‐8 and −173 G>C MIF polymorphisms in non‐segmental vitiligo and its correlation with serum concentrations, histopathological levels of the protein of patients samples, and disease activity was evaluated." (PMID 32705792, 2020). "To clarify, as definitively as possible, the contribution of MIF promoter polymorphisms to vitiligo risk and phenotype in this study, we also determined the relationship between −794 CATT5‐8 and −173 G>C polymorphisms and the serum levels of MIF." (PMID 32705792, 2020). "A goiter-developmental model incorporating genetic (MIF SNP rs755622) and environmental risk factors (gender, radioiodine treatment, thyroid gland surgery and vitiligo) significantly increased the prediction accuracy." (PMID 24667663, 2014). "Results suggest that in the untreated group, the rs755622 SNP in MIF is also associated with age, thyroid gland surgery and vitiligo." (PMID 24667663, 2014). "Taking GG genotype and G allele as references, MIF GC, CC, (GC + CC) genotypes, and C allele demonstrated a substantially higher occurrence in all patients when compared to controls, with a higher risk of developing vitiligo within healthy control subjects." (PMID 40445486, 2025). "However, the impact of MIF gene polymorphism in developing vitiligo relies on only two studies: one in China and the other in Western Mexico." (PMID 40445486, 2025). "MIF polymorphisms can also increase the risk of developing vitiligo." (PMID 37731844, 2023). "The presence of vitiligo as an autoimmune-associated pathology was correlated with a moderately severe form of Graves’ disease, and the C/G and G/C alleles within the MIF gene polymorphism were correlated with the existence of vitiligo in patients with untreated Graves’ disease." (PMID 36556267, 2022). "MIF (GC + CC) genotypes were considered as independent predictors for severity extent within vitiligo patients." (PMID 40445486, 2025).
vitiligo (continued). "MIF (GC + CC) genotypes were considered as independent predictors for vitiligo development within healthy control subjects." (PMID 40445486, 2025). "Serum MIF is elevated both in AA (N = 22) and vitiligo (N = 20), as compared with controls (N = 20), and correlates with disease severity." (PMID 38673994, 2024). "Results showed significantly higher serum levels of sCD27 (p < 0.001) and MIF (p = 0.01) in vitiligo patients than in the control group." (PMID 38666916, 2024). "Further studies are needed to confirm or refute the role of MIF in vitiligo pathogenesis via immune privilege collapse in the same way as in AA pathogenesis." (PMID 38673994, 2024). "A significant positive correlation was seen for active vitiligo patients as an indicator of disease severity for both MIF (p = 0.002) and sCD27 (p < 0.001)." (PMID 38666916, 2024). "Collectively, the interaction analyses highlighted the role of peripheral blood circulating immune cells in vitiligo patients in promoting immune cell hyperactivation through MIF and CXCL signaling pathways." (PMID 38077333, 2023). "Significantly elevated serum MIF levels and MIF mRNA expression have been found in vitiligo patients, suggesting that MIF is involved in the pathogenesis of vitiligo." (PMID 38077333, 2023). "The authors concluded that MIF would have an important role in vitiligo since the mean serum MIF level of patients was higher than that of controls." (PMID 32705792, 2020). "Significantly higher levels of MIF protein were found in the samples from patients with vitiligo, especially in the depigmented skin of patients with disease activity." (PMID 32705792, 2020). "The previously exposed evidence presents severe limitations to be able to define the role of MIF in vitiligo." (PMID 32705792, 2020). "Even more significant, the degree of activity of vitiligo showed a correlation with the presence of −794 CATT5‐8 and the −173 G>C polymorphisms and the serum concentrations of MIF." (PMID 32705792, 2020). "Similar to Ma and Farag, a significant difference in MIF concentrations between the active vitiligo patients compared to the stable ones wAS found." (PMID 32705792, 2020). "The depigmented skin from patients with active vitiligo showed a high expression of MIF, which was significantly higher than the appearance of the protein in the rest of the groups (p < 0.05 in all cases)." (PMID 32705792, 2020). "That is why, in this study, we also evaluate the presence of MIF protein in histopathological samples of patients with vitiligo and compare them with the expression in healthy tissues." (PMID 32705792, 2020). "Both the depigmented skin and perilesional skin of the 25 patients with vitiligo had higher values of MIF expression compared to the skin sample of control subjects (p < 0.01)." (PMID 32705792, 2020). "Based on the results of our study, we can conclude that MIF could play an important role in the pathophysiology of vitiligo and serve as an indicator of disease severity." (PMID 40445486, 2025). "Very few studies have evaluated the elevated serum levels of MIF in patients of vitiligo." (PMID 40445486, 2025). "In addition, the severity of vitiligo was positively correlated with serum MIF concentrations and MIF mRNA levels in PBMCs." (PMID 37731844, 2023). "Moreover, patients with active vitiligo and a score of the activity index equal to or greater (≥) than +3 had higher concentrations of MIF [p <0.0001 compared to +2 punctuation and p = 0.0008 compared to +1 score];." (PMID 32705792, 2020). "This evidence and our results open new avenues about the possible role of MIF in vitiligo." (PMID 32705792, 2020). "The association between MIF polymorphisms (−794 CATT5‐8 and −173 G>C), MIF in situ expression, and MIF serum concentrations with susceptibility and disease activity in patients with non‐segmental vitiligo (NSV) from western Mexico." (PMID 32705792, 2020).
vitiligo (continued). "Also, there was a significant difference between progressive and stable patients, and the vitiligo area severity index score (VASI) of patients correlated positively with changes in both serum MIF concentrations and mRNA levels." (PMID 32705792, 2020). "The depigmented skin from patients with active vitiligo showed a high expression of MIF." (PMID 32705792, 2020). "The Sutton nevus samples had high MIF levels compared to control subjects (p = 0.002); however, the average optical densities were significantly lower compared to the samples from the active vitiligo lesions (p = 0.03)." (PMID 32705792, 2020). "Molecular studies are required to evaluate whether MIF has a protective role in patients with active vitiligo and short evolution trying to regulate the inflammatory response or if MIF is a part of the courtship of pro‐inflammatory cytokines that cause the clinical manifestations." (PMID 32705792, 2020). "Serum MIF concentrations and MIF mRNA levels were significantly highly elevated in patients with vitiligo vulgaris compared to controls, in generalized vitiligo compared to the localized one, and it was a positive correlation with the vitiligo type, duration, and severity." (PMID 32705792, 2020). "Moreover, serum MIF concentrations were not related to the presence of polymorphisms in patients with vitiligo." (PMID 32705792, 2020). "Therefore, the MIF and macrophage loop may partially contribute to the etiology of vitiligo." (PMID 40445486, 2025). "A cross-sectional study sought to validate serum soluble CD27 (sCD27) and macrophage Migration Inhibitory Factor (MIF) using 22 active and 10 stable vitiligo patients and 32 healthy controls." (PMID 38666916, 2024). "Therefore, we hypothesized that T cells secreted MIF to promote monocyte activation and proinflammatory cytokine secretion to maintain the inflammatory state of the peripheral immune microenvironment in vitiligo patients." (PMID 38077333, 2023). "The downstream signaling pathway of MIF, including AKT and ERK, was also involved in the pathogenesis of vitiligo." (PMID 37731844, 2023). "Downregulation of MIF can inhibit the activation and proliferation of CD8 + T cells in the lymph nodes of mice with vitiligo, and this effect extends to the CD8 T cells in the peripheral blood mononuclear cells of patients with vitiligo." (PMID 40703229, 2025). "In this study, we found that among lncRNAs, the expression of LOC100506314 was increased in T cells from patients with vitiligo and participated in the immunopathogenesis of vitiligo via binding to STAT3 and MIF, which could affect its downstream signaling." (PMID 37731844, 2023). "The macrophage migration inhibiting factor (MIF) is a protein that promotes the activation of immune cells and the production of other proinflammatory cytokines such as TNF‐α, IL‐1β, and IFN‐γ, which have proposed to play an essential role in the pathogenesis of vitiligo." (PMID 32705792, 2020).